CD4 (CD4 molecule)
Diseases named in the same sentence as CD4 in open-access papers (continued):
Sharing a sentence is not in itself a finding about the gene and the disease.
tumor (continued). "Moreover, the adoptive transfer of CD4+ T-cell populations has shown that these cells can cause tumor regression." (PMID 35154479, 2022). "Our data showed that the top three cancers were BLCA, BRCA, and COAD, where CD73 expression in the tumor microenvironment is associated with infiltration of immune cells, including B cell, CD4 and CD8 T cell, dendritic cell, macrophage, and neutrophil (p < 0.05)." (PMID 36428755, 2022). "However, the tumor growth in Asm-deficient mice was still significantly enhanced compared to WT littermates after CD4+ T cell depletion." (PMID 36426850, 2022). "Moreover, PAPPA2 mutation was correlated with enhanced anti‐tumour immunity including higher activated CD4 memory T cells level, lower Treg cells level, and upregulated DNA damage repair pathways." (PMID 35811392, 2022). "Moreover, tumor-infiltrating follicular CD4+ T-cells near CD8+ T-cells have been associated with better prognosis in HR+ BC37." (PMID 35676750, 2022). "In this study, we comprehensively profiled the tumor microenvironment in the high-risk and low-risk groups, and we found a higher proportion of activated CD4_T_cell, and macrophages, and a lower proportion of activated CD8_T_cells and CD56bright_natural_killer_cells compared to the low-risk group." (PMID 36536232, 2022). "CLEC10A can recognize tumor-associated antigens and pass them to CD4 T cells." (PMID 35281077, 2022). "However, the proportion analysis of tumor-infiltrating immune cells revealed a significantly lower abundance of resting CD4+ T memory cells in the high-risk group." (PMID 36544784, 2022). "Importantly, CD4+ Th1 cells have been preclinically and clinically implicated in maintaining control of tumor growth, even in tumor models that lack MHC class II expression." (PMID 35289317, 2022). "An upregulation of HLA-DRA expression is associated with antitumour immune response, whereby it functions in presenting tumour-associated antigens (TAA) on cancer cells that trigger CD4+ Th1 cells and NK cells, with the production of IFN-γ, an antitumour cytokine." (PMID 35208514, 2022). "Although BAY-I treatment had similar effects on tumor-associated CD4+ T cell and Treg cells in the Pten-null;Cd8-KO mice, the increased intratumoral CD8+ and GZMb+ cells seen in the Pten-null mice upon BAY-I treatment was nearly completely abolished in Pten-null;Cd8-KO mice." (PMID 35013322, 2022). "The increased abundance of IFNγ secreting CD4+ TILs in CaMKK2-deficient mice, in addition to chemotactic signals from DC-like TAMs (Cxcl9, Cxcl10), may explain the enhanced tumor penetrance seen by CD4+ and myeloid cells in the setting of CaMKK2 deficiency." (PMID 36309495, 2022). "Interestingly, NEMO∆hepa/Tlr4−/− mice displayed a reduced abundance of MDSCs and an increase in CD4+ T cells, which was linked to a lower tumor burden at 52 weeks." (PMID 35803930, 2022). "The poor survival associated with high MMP1 expression + high macrophage/MDSC/T cell CD4 + infiltration also indicated that these risk factors might contribute to tumor progression synergistically." (PMID 35948625, 2022). "To test whether the tumor-specific CD4 T cells were the source of the crucial IFNγ, we treated tumor-bearing mice with IFNγ deficient Marilyn CD4 T cells and found that, similarly to the IFNγ blocking experiment, most of the antitumor effect was lost." (PMID 35903540, 2022). "CD4+ FoxP3+ Tregs, which exert a suppressive effect on effector T cells implicated in tumor surveillance, have been shown to account for a large proportion of tumor-infiltrating lymphocytes (TILs) in melanoma and breast cancer that do not respond to ICI." (PMID 36678712, 2022). "Furthermore, the lncRNA risk score showed a higher correlation with the tumor cells such as the CD4 memory-activated T cells, CD8 T cells, and naive B cells, which indicated an active anti-tumor immune response." (PMID 36092958, 2022).
tumor (continued). "It was found that different types of mutations in the risk model genes could alter tumor infiltrating immune cells such as CD4+ T cells, CD8+ T cells and so on." (PMID 36581948, 2022). "As CD4+ Treg cells promote tumor immunosuppression and are associated with poor prognosis, novel immunotherapy targets for Treg cells may improve the treatment of ECCA." (PMID 35562760, 2022). "Moreover, tumor-infiltrating B cells have also been associated with global TILs, CD4+ and CD8+ T cells, higher tumor grade and proliferation, and HR negativity." (PMID 36551522, 2022). "HLA Class II alleles are highly associated with the CD4+ T cells; CD4+ T cells primarily mediate anti-tumor immunity by providing help for CD8+ CTL and antibody responses, as well as via secretion of effector cytokines such as interferon-γ (IFNγ) and tumor necrosis factor-α (TNFα)." (PMID 35967400, 2022). "Our Spearman’s correlation tests of immune subpopulations reported a negative correlation (ρ < 0) between PTEN mutations and the expression of infiltrating T cell CD4+ Th 1 (ρ = −0.245), Th 2 (ρ = −0.225), and NK cells (ρ = −0.163) within the tumor microenvironment." (PMID 35448032, 2022). "The MDSCs inhibit the antitumor immunity via various mechanisms including the crosstalk with other immunosuppressive cell types such as regulatory T cells (Tregs), M2 differentiated tumor-associated macrophages (TAMs) and T helper 2 (Th2) differentiated CD4+ T cells." (PMID 36685537, 2022). "In general, CD8+ cytotoxic T cells (CTLs), CD4+ helper T cells, and natural killer cells are expected to have anti-tumor activity, while Treg cells, tumor-associated macrophages (TAMs), and myeloid-derived suppressor cells (MDSCs) are associated with tumor immunosuppression." (PMID 36524123, 2022). "Tumor-associated macrophages (TAMs) and dendritic cells (DCs), as the main components of antigen-presenting cells, play an indispensable role in the adaptive immune response by capturing and presenting tumor antigens to CD4+ and CD8+ T cells." (PMID 35874784, 2022). "The unique biological role of cytotoxic CD4+ T cells still needs considerable investigation, especially the mechanism underlying cell population development and regulation and the mechanism by which cell populations contribute to tumour cell death." (PMID 36159866, 2022). "Exhaustion-associated markers on activated CD4+ T cells were upregulated during tumor progression, suggesting that these CD4+ T cells may also be responsive to PD-L1 blockade therapies." (PMID 35784297, 2022). "Recently, several clinical studies have shown that the peripheral blood CD4+ T subsets may be associated with tumor objective response for immunotherapy." (PMID 35844502, 2022). "The presence of PD-L1+ tumor-associated macrophages (TAMs) and PD-1+ TILs indicates that the pathway may be activated in 20–35% of cases where PD-1 is expressed on CD4+ and CD8+ T-lymphocytes upon antigen receptor signaling." (PMID 36136862, 2022). "Our results showed associations between Piezo2 and CD4+ T memory cells, mast cells, and dendritic cells, suggesting that Piezo2 may involve in tumor progression by influencing immune infiltration or regulating immune cell function." (PMID 35991548, 2022). "Another alteration in the TME induced by TGF-β activation is changes in several stromal cells, including cancer-associated fibroblasts, natural killer cells, tumor-associated neutrophils, tumor-associated macrophages, naïve CD4+ T cells, type 1 T helper cells, and regulatory T lymphocytes." (PMID 36551305, 2022). "Furthermore, tumor-associated natural killer cells, B cells, and CD4 Foxp3-positive T cells were reported by two and myeloid-derived suppressor cells, granulocytes, mast cells, and leukocytes by one publication." (PMID 34845660, 2022).
tumor (continued). "Moreover, they found a dynamic shift in the tumor microenvironment over time, with the pre-cancerous lesions exhibiting high concentrations of CD4+ and CD8+ lymphocytes and special cancer-associated fibroblasts (CAFs) called myofibroblasts (myCAFs)." (PMID 36230515, 2022). "Immune cells mainly comprise CD8+ T, CD4+ T, regulatory T, myeloid suppressor, and NK cells, as well as tumor-associated macrophages and neutrophils, all of which interact to exert anti- or pro-tumor effects." (PMID 36072666, 2022). "Moreover, the expressions of CXCL14, CCL20, CCL24, and CCL26 were associated with tumor purity and infiltration of CD4+ T cell, CD8+ T cell, B cell, macrophage, dendritic cell, and neutrophil in PCa." (PMID 36275733, 2022). "CD4+ T cell infiltration of the tumour stroma was also associated with improved overall survival." (PMID 35267589, 2022). "Interestingly, higher 16S rRNA gene abundance was associated with increased CD8+ T cells, NKT cells, central memory CD4+ and regulatory T cells, the latter of which have been implicated in tumor immunosuppression." (PMID 35803930, 2022). "In this scenario, the PR20.2-expressing tumors formed in PR_Ai2mut-immunized mice could be infiltrated by CD4+ T cells inefficient in or incapable of killing tumor cells expressing the PR V82A mutant, but causing local inflammation and enhancing tumor growth." (PMID 36612231, 2022). "Additional correlation analyses showed that IL7R expression was significantly associated with markers of cells involved in immunosuppression such as CD68, CD163, MRC1, and IL10 (tumor‐associated macrophages), CD4, FOXP3 (regulator T lymphocytes) and CD274 (PD‐L1)." (PMID 36054746, 2022). "In the tumor microenvironment, CD8+ T subtypes in T cells can cause killing effect on tumor cells, and CD4+ T cells can regulate or assist other lymphocytes to function, while Treg cells can inhibit the activation and proliferation of CD4+ T cells and CD8+ T cells in immune system." (PMID 35590394, 2022). "In addition, activation of GCN2 and inactivation of mTORC contributes to the differentiation, activation and maintenance of the suppressive state of regulatory CD4 T (Tregs) cells that further contribute to tumor-associated immunosuppression." (PMID 35173722, 2022). "Oral supplementation with a probiotic containing Lactobacillus reuteri alone was sufficient to inhibit BC tumorigenesis in murine models genetically predisposed to neoplasia and fed a cancer-promoting western diet through microbially-initiated CD4+/CD25+ lymphocytes." (PMID 36505861, 2022). "Our imaging suggested similar interactions may be occurring in human non-tumor-associated dura as we observed co-localization of CD4+ T cells and HLA-DRA+ cells in addition to CD8+ T cells and CD163+ macrophages near CD31+ stained vasculature." (PMID 35534852, 2022). "The abundance of CD8+, activated CD4+ memory T cells, and DC cells was downregulated, while M0 microphages, B naïve cells, and Tregs were \ significantly upregulated in the high-risk group, which showed a pro-tumor tendency." (PMID 35464857, 2022). "In addition, the anti-CD25 antibody PC61 caused the specific elimination of CD4+CD25hiFoxp3+ Tregs, resulting in an effective anti-tumor immune response." (PMID 36466873, 2022). "These associations suggest that CD4 and FoxP3 biomarkers may be used as a measure of a pro‐tumor immune infiltrate." (PMID 34626165, 2022). "When Tregs are depleted, cDC2s could potently activate CD4+T cells to kill tumor cells and are associated with a favorable prognosis in HNSCC and melanoma." (PMID 36246629, 2022). "Furthermore, the expression of FAM72A and mTOR was significantly associated with the abundance of some tumor-infiltrating immune cells, especially CD4+ T cells." (PMID 36483027, 2022). "CD4 Treg cells harm anti-tumor immunity by inhibiting tumor-associated antigens." (PMID 35552266, 2022).
tumor (continued). "For example, the presence of CXCL10 or CXCL11 within the tumor is associated with a CD8 T-cell number but also with the CD4 Treg cell accumulation with immunosuppressive and cancer-initiating effects, thus rendering it difficult to use such chemokines as prognostic factors." (PMID 36429101, 2022). "Tumor antigens and damage-associated molecular patterns (DAMPs) are released after local cryo-thermal therapy and induce strong neoantigen-specific Th1-dominant CD4+ T-cell antitumor immunity." (PMID 35874660, 2022). "Furthermore, a population of cytotoxic CD4+ T cells was characterized in bladder cancer that directly killed autologous tumor cells in an HLA-II-dependent manner and was associated with improved response to ICB27." (PMID 35831288, 2022). "Furthermore, CXCL1 elevation promoted the migration of M2-tumor associated macrophages (TAMs) while disrupting the aggregation of CD4+ and CD8+ T cells at tumor sites." (PMID 36434686, 2022). "Finally, these PD-1+ICOS+ CD4+ Th TILs were shown to recognize both tumor-associated antigens and tumor-specific neoantigens." (PMID 35439168, 2022). "Additionally, the high infiltration of exhausted CD4+ T cells often causes tumor cells to evade the attack of the immune system, making the overall immune microenvironment present a state of exhausted cells that are enriched but have lost toxic function." (PMID 35456499, 2022). "However, the relationship between B7-H5 and other immune cells such as CD4+ T cells, tumor-associated cells (TAMs), and MDSCs in the CRC TME should be further clarified." (PMID 34537815, 2021). "In addition, tumor-associated macrophages (TAMs) are involved in inhibiting the activity of immune-effector cells such as CD4+ T cells, CD8+ T cells, and natural killer cells in tumor microenvironments." (PMID 34395265, 2021). "Furthermore, gene transfer of CIITA into tumor cells resulted in a stimulation of tumor specific CD4+ T cells in vivo associated with a long-lasting protective immunity, as well as an increased repertoire of tumor-associated HLA class II antigens." (PMID 34359808, 2021). "In addition, a strong association of tumor-infiltrating CD4+ cells and the presence of CD44s expression in tumor samples was observed." (PMID 34885185, 2021). "Furthermore, FATS deficiency increased IFN-γ and TNF levels in B16 tumor-infiltrating CD4+ T cells, suggesting enhanced Th1 responses." (PMID 34262035, 2021). "The first evidence regarding their function in inhibiting the anti-tumor immunity emerged 20 years ago, when two independent groups demonstrated that elimination of CD25+CD4+ T cells in mice is associated with enhanced anti-tumor immune responsiveness and tumor regression." (PMID 34539668, 2021). "We found that positively associated with Macrophage, Macrophage M0, Macrophage M2, and Monocyte in the high‐risk group, a higher positively associated with tumor‐infiltrating immune cells, such as B cells, Macrophage M1, CD4+ T cells and CD8+ T cells in the low‐risk group." (PMID 34378851, 2021). "The results showed that the low-risk group was related to more tumor-infiltrating immune cells such as CD8+ T cells, CD4+ T cells, B cells, and neutrophils, whereas the high-risk group was related to more tumor-infiltrating immune cells such as NK cells, macrophages, and Tregs." (PMID 34610581, 2021). "Besides, lower CD4 Naïve and higher CD4 Memory and DC infiltration levels were associated with advanced tumor stage, higher pathological stage and histological grade, and metastasis." (PMID 33390830, 2021). "All other treatments that targeted tumor-associated myeloid cells or checkpoint showed increased accumulation of CD4 and CD8 cells in the tumors but myeloid cell populations including MDSCs, CD11b+ cells, and macrophages showed insignificant changes in the TME compared to that of control tumors." (PMID 33544755, 2021).
tumor (continued). "In addition, AZB appeared to have a positive effect on the tumour itself (in the form of pathomorphosis induction), associated with a subpopulation of intra-tumoural CD4+ lymphocytes and decreased CD8+/CD4+ index." (PMID 34568029, 2021). "Meanwhile, ADQ remodeled the immunosuppressive tumor microenvironment (TME) by increasing the infiltration of tumor-infiltrating lymphocytes (TILs) and cytotoxic CD8+ T cells, and decreasing the infiltration of Tregs, naive CD4+ T cells, and tumor-associated macrophages (TAMs)." (PMID 34461944, 2021). "Hamada16 has also reported that TIL-present tumor immunity in the microenvironment subtypes of colorectal cancer are associated with better responsiveness to cancer immunotherapy, and low CD4+ and CD8+ TIL counts have also been found to predict extremely poor HCC-specific survival." (PMID 33710817, 2021). "In the present study, we found that LUAD patients in the high-risk group revealed higher infiltration of tumor-infiltrating immune cells, such as M0 macrophages, neutrophils, resting NK cells, and activated memory CD4 T cells, than patients in the low-risk group." (PMID 34419075, 2021). "Additionally, CD4+ T cells that encounter mutated genes such as fibronectin are involved in tumor metastasis." (PMID 34204474, 2021). "In contrast, the degree of M1 macrophage infiltration increased significantly in low-risk group, indicating that CD4+ memory T cells and activated mast cells may be markers of poor outcome and may help tumor immune escape in the immune microenvironment." (PMID 34868310, 2021). "Moreover, the lower presence of these two CD4+ TNFR2+ sub-populations after chemotherapy tended to associate with reduced tumor growth." (PMID 34201054, 2021). "Loss of Th1 responses leading to tumor progression could point towards increase in apoptosis of CD4+ T cells via Fas pathway or tolerance to tumor antigens (for instance, CTLA-4 and PD-1)." (PMID 34899753, 2021). "In addition, the study shows that COL1A1 expression is closely related with tumor purity and linked to CD4+ T cells, Macrophage, Neutrophil and Dendritic cell in LUAD and LUSC." (PMID 33850663, 2021). "On the other hand, TIM-3 was associated with poor prognosis and suppression of anti-tumor function with an inhibitory role in T cells as TIM-3-expressing CD4+ and CD8+ T cells produce a weak amount of cytokine with less proliferative phenotype in response to antigen stimulation." (PMID 34572799, 2021). "These were also associated with an altered frequency of tumor infiltrating CD4+ and CD8+ T cells." (PMID 34359808, 2021). "In addition, a strong association between tumor-infiltrating CD4+ cells and the presence of CD44s expression in tumor samples was observed." (PMID 34885185, 2021). "Also, long term response in a patient adoptively transferred with TILs correlated to expansion and persistence of CD4 T cells directed against tumor specific mutation BRAFV600E." (PMID 34140957, 2021). "However, in another study, TACE increased the frequency of tumor-specific CD4+ T cells, which was associated with improved clinical outcomes." (PMID 34575463, 2021). "Functional characterization confirmed this signature could predict immune-related phenotype and was associated with immune cell infiltration (i.e., macrophages M0, M1, Tregs, CD4 memory resting cells, and neutrophils), tumor mutation burden (TMB)." (PMID 34659346, 2021). "Tumor-infiltrating Tregs, which may constitute up to 20–30% of the total CD4+ population of the tumor, are strongly associated with advanced cancer stage and poor prognosis." (PMID 34079545, 2021). "Moreover, the RNAseq analysis revealed 341 significantly dysregulated genes in tumor associated CD4+ T cells compared to blood." (PMID 34012510, 2021). "CD73 is associated with immune suppression and tumor progression involving CD4+ T cell suppression." (PMID 33763348, 2021).